IL1B (interleukin 1 beta)
Diseases named in the same sentence as IL1B in open-access papers (continued):
Sharing a sentence is not in itself a finding about the gene and the disease.
Sepsis (continued). "In vivo studies using mouse models of LPS-induced sepsis confirmed that fucoxanthin decreases the levels of inflammatory cytokines like IL-6 and IL-1β by regulating the NF-κB signaling pathway, thus suggesting its therapeutic potential against sepsis and acute inflammation." (PMID 39065808, 2024). "Studies have shown that the activation of the NLR family pyrin domain containing 3 (NLRP3) inflammasome and subsequent pyroptosis in macrophages can lead to the release of proinflammatory factors, such as IL-1β, thereby augmenting inflammatory responses observed in conditions like sepsis." (PMID 38705396, 2024). "Additionally, our findings demonstrated that LBT effectively downregulated the levels of IL-6, TNF-α, and IL-1β in serum samples while inhibiting inflammatory cell infiltration within lung and liver tissues induced by LPS-induced sepsis." (PMID 38799158, 2024). "Moreover, sepsis patients show increased serum LDH levels which is positively correlated with serum lactate, IL-1β and 28-day mortality, thereby suggesting that glucose metabolic reprogramming of immune cells contributes to sepsis mortality." (PMID 39468303, 2024). "Similarly, UBC9ΔDC mice in the cecal ligation and puncture (CLP) sepsis model exhibit higher mortality rates than WT mice in the CLP sepsis model, with significantly elevated levels of IL-18 and IL-1β in plasma." (PMID 39234245, 2024). "We compared the effects of two treatments, antibiotics and FMT, on the levels of inflammatory factors, including the proinflammatory factors TNF-ɑ, IFN-γ, IL-1b, and IL-6, and the anti-inflammatory factor IL-10, in the serum and alveolar lavage fluid of pneumonia-induced sepsis model mice." (PMID 38903943, 2024). "Consequently, our results highlight the remarkable ability of LBT to downregulate the production of IL-6, TNF-α, and IL-1β while alleviating LPS-induced sepsis through its impact on macrophage-mediated inflammatory cytokine production." (PMID 38799158, 2024). "We analyzed whether the polymorphism was correlated with the cytokine expression of IL1β, IFNα2, IFNγ, TNF-α, IL-33, IL12p70, MCP-1, IL-6, IL-10, IL-17a, IL-18, or IL-23 to further investigate the effect of the polymorphism in sepsis patients." (PMID 38338680, 2024). "Similarly, H3S28p was found to be more enriched in TNFA and IL-1B promoters at 1 dpb in patients that developed sepsis." (PMID 39768289, 2024). "Despite the importance of PGE2 in producing fever responses, fever observed during mild sepsis may be also result of a prostaglandin-independent pathway mediated by IL-1β." (PMID 39522078, 2024). "While some studies have identified associations between specific metabolites and inflammatory factors, such as the link between succinate and IL-1β production, the precise mechanisms and the collective impact of these interactions on sepsis outcomes are not well understood." (PMID 39205680, 2024). "Using cytokine injections and perturbations in vivo, we discovered a hierarchical cytokine module composed of TNF, IL-18, IFN-γ and IL-1β that sufficed to explain most of the organism-wide response to sepsis, ranging from genes to cells to tissue physiology and host fitness." (PMID 38191855, 2024). "Additionally, it has been shown that TRPA1 can mediate sepsis-induced immunosuppression in response to IL-1B." (PMID 38731999, 2024). "Along with these changes, the mRNA levels of inflammatory mediators such as tumor necrosis factor-α (Tnf-α), chemokine ligand 2 (Ccl2), interleukin-6 (Il-6), interleukin-1β (Il-1β), and nitric oxide synthase 2 (Nos2) also demonstrated a marked elevation in the sepsis group." (PMID 38705396, 2024). "In vivo studies demonstrated that HIPK2-deficient mice are more susceptible to lipopolysaccharide (LPS)-induced endotoxemia and cecal ligation and puncture (CLP)-induced sepsis, with increased serum concentration of proinflammatory IL-6, IL-1β and TNF-α cytokines." (PMID 39062921, 2024).
Sepsis (continued). "Likewise, this study observed that a combination of 1,25D3 and butyrate enhanced the autophagy gene ATG16L1 but suppressed proinflammatory IL-1β mRNA expression in chemotherapy-receiving mice complicated with gut-derived P. aeruginosa sepsis." (PMID 38790988, 2024). "Additionally, sepsis is characterized by increased release of pro-inflammatory cytokines, such as IL-1β, IL-6, and TNF-α." (PMID 39337575, 2024). "Notably, gene expression of in particular CXCL2 was further enhanced by combined stimulation of hepatocytes with bile acids and IL-1β, highlighting the role of bile acids as DAMPS in the context of sepsis-associated cholestasis." (PMID 39680527, 2024). "During sepsis, the innate immune system acts as the primary defense for the host, with immune cells like monocytes/macrophages becoming hyperactivated, releasing copious inflammatory cytokines, such as interleukin (IL)-1β, IL-6 and interferon-gamma (IFN-γ)." (PMID 39320524, 2024). "Interestingly, Tocilizumab reduces not only inflammasome activation, but also IL1β production, as has been demonstrated in a sepsis cell model." (PMID 39346556, 2024). "In addition sepsis is accompanied by a cytokine storm, and interleukin-6 IL-6), IL-8, IL-1β, IFN-α2, and IL-33 are released." (PMID 38279209, 2024). "In addition, Pearson correlation analysis showed a positive correlation between circMAPK1 and IL-1β/IL-18 levels in patients with sepsis-induced lung injury, suggesting the potential role of circMAPK1 in modulating inflammation in sepsis-induced lung injury." (PMID 39300342, 2024). "Vincamine exhibited hepato-protective potential during CLP-induced sepsis via the cross-connection of antioxidant, anti-inflammatory, and anti-apoptotic activities by modulating TNFα/IL-6/IL-1β/Nrf-2/Keap-1 and regulating bax/bcl2/cleaved caspase 3 signaling pathways." (PMID 39174578, 2024). "Additionally, LPS caused elevated levels of TNF-α, IL-1β, IL-6, and MCP-1 in the supernatant of HK-2 cells, showing that there was increased inflammation in our cellular models of sepsis." (PMID 37085762, 2023). "Inflammasome activation plays a vital role in hyperinflammation during sepsis, as it triggers the production and release of proinflammatory cytokines, such as IL-1β (Interleukin 1β) and IL-18 (Interleukin 18), and induces inflammatory cellular death, including pyroptosis and necroptosis." (PMID 37711629, 2023). "Inflammatory hallmark cytokines IL-1β, IL-6, and TNF-α constitute the cytokine storm during sepsis." (PMID 38152336, 2023). "Macrophages can recognize LPS released by Gram-negative bacteria through TLRs, leading to excessive expression of inflammatory factors, including IL-1β, TNF-α, and IL-6, which are considered the leading cause of multiple organ dysfunction in the early stage of sepsis." (PMID 37840694, 2023). "Studies have shown that IMD could reduce the expression of major inflammatory factors in sepsis by regulating the NLRP3/Caspase-1/IL-1β pathway, thereby exerting a protective effect against sepsis-induced cardiac dysfunction." (PMID 37745233, 2023). "First, tissue concentrations of IL-1β in sepsis are unknown and the existence of such a reservoir is unestablished." (PMID 37928695, 2023). "As predicted, Neu_ Il1b exhibited higher ROS scores in response to sepsis." (PMID 37808269, 2023). "The sepsis animal models have been demonstrated that increase level of IL-1β." (PMID 37494665, 2023). "The results of the current study also confirmed that SIN could induce increased secretion of TNF-α, IL-6, and IL-1β in CLP-induced sepsis." (PMID 37388447, 2023). "During pyroptosis, IL-1β and IL-18, both important inflammatory cytokines in sepsis, are released." (PMID 36756123, 2023).
Sepsis (continued). "Our results indicated that Daph treatment improved survival rate and alleviated pulmonary pathological damage of the sepsis mice, as well as reduced the excessive release of pro-inflammatory cytokines IL-1β, IL-18, IL-6, iNOS and chemokines MCP-1 regulated by MAPK/NF-κB pathway in pulmonary injury." (PMID 36998049, 2023). "However, the Ticagrelor-treated group showed significantly decreased expression of the inflammatory markers IL-6 and IL-1β compared to the sepsis group." (PMID 37675176, 2023). "Furthermore, ODZ administration significantly reduced MSU-induced IL-1β release and the mortality rate of mice with LPS-induced sepsis." (PMID 37047051, 2023). "In addition, pneumonia-induced sepsis patients showed a markedly enhanced expression of IL-1β and IL-18 from plasma in comparison to pneumonia patients without sepsis and healthy people." (PMID 36923408, 2023). "Reduced IL‐1β serum levels in septic Nlrp3 KO mice are accompanied by reduced cardiac and cardiomyocyte atrophy, improved cardiac diastolic and systolic function, and increased sepsis survival compared with septic WT mice." (PMID 37904696, 2023). "We have found a new solute carrier called SLC38A6, which is essential for sepsis-associated pulmonary inflammation, SLC38A6 may mediate inflammation by directly participating in the maintenance of IL-1β in macrophages." (PMID 36707853, 2023). "In a sepsis model characterized by significant systemic inflammation, sleep in rats exhibited a fragmented pattern, which was found to be influenced by elevated mRNA and protein levels of cytokines, including IL-1β, IL-6, and TNF-α, in the nervous system." (PMID 37872570, 2023). "Higher IL-1β amounts in sepsis compared to COVID-19 carries implications." (PMID 37928695, 2023). "The levels of proinflammatory cytokines including IL-6, IL-1β, Il-17A and TNF-α, as detected by quantitative PCR or enzyme-linked immunosorbent assay (ELISA), were decreased in lung tissue of sepsis mice upon treatment of JHD, as compared with their counterpart with no treatment." (PMID 37081964, 2023). "In response, we conducted a systematic review and meta-analysis that quantified IL-1 levels in sepsis and determined a mean 21.8 pg./mL IL-1β in the circulation in sepsis patients, demonstrating IL-1β blood levels in sepsis far exceed those in COVID-19 (Step 2d)." (PMID 37928695, 2023). "verified that the miR-125-mediation MCEMP1 suppression could decrease the sera levels of TNF-α, IL-1β, and IL-6, and the programmed cell death facilitated the T leukomonocyte activity, hence attenuating the immune activity of sepsis mice." (PMID 37359526, 2023). "Inflammatory cytokines are linked to the progression of sepsis by causing an excessive inflammatory response, and HMGB1 functions as a proinflammatory molecule to increase the secretion of inflammatory cytokines such as TNF-α, IL-6 and IL-1β." (PMID 38026444, 2023). "Similarly, levels of IL-6 and IL-1β in the lung tissue were significantly higher (p<0.05) in the sepsis group compared to the sham group." (PMID 37675176, 2023). "Elevated IL-1β and IL-6 in Alzheimer’s disease echo the neuroinflammation seen in sepsis." (PMID 36844403, 2023). "Our results show that not only the systematic Slc38a6 knock-out but also Slc38a6 specific knock-out in LyzCRE cells could ameliorate LPS induced sepsis-associated pulmonary inflammation severity, and decrease inflammatory cytokines, such as TNF-α and IL-1β." (PMID 36707853, 2023). "Specimen collections occurred after 24 h of severe sepsis giving time for ferritin levels to reach their peak; however, cytokines expected to peak in the first 6 h of sepsis such as IL-1β and TNF may have been higher if sampled earlier." (PMID 37674218, 2023). "For example, over-released IL-18 caused diabetic retinopathy by increasing retinal vascular permeability, and IL-1β could destroy vascular integrity during sepsis-induced lung injury through suppressing VE-cadherin expression in lung endothelial cell." (PMID 36923408, 2023).
Sepsis (continued). "Moreover, it was demonstrated that NET-derived HMGB1 induces macrophage pyroptosis and IL-1β release via RAGE in a mouse model of sepsis." (PMID 36776857, 2023). "Another study considered IL-1β inferior at predicting sepsis when compared to CRP, TNF and IL-6." (PMID 36769133, 2023). "When sepsis begins, upregulation and activation of HATs open chromatin structure and promote transcription of a large number of pro-inflammatory genes, including TNFα, IL-1β, and iNOs." (PMID 36774341, 2023). "Future research should focus on elucidating the mechanism of bi-directional signal transduction between IL-1β and necroptosis and exploring the potential therapeutic window for neurodevelopment improvement by inhibiting IL-1β production in newborns with sepsis." (PMID 37834141, 2023). "The Mg‐Tob motor conveyed satisfactory anti‐inflammation protection by neutralizing multiple pro‐inflammatory cytokines involving TNF‐α, IL‐6 and IL‐1β both in vitro and in vivo, which ensured it as an excellent candidate to prevent the development of highly heterogeneous inflammation in sepsis." (PMID 37818787, 2023). "LPS administration in mice is a widely used animal model to study sepsis, which partially mimics some of the initial clinical features in humans, including the serum increases of pro-inflammatory cytokines, such as TNFα, IL-6 and IL-1b." (PMID 35887265, 2022). "The authors noticed that both SARS-CoV-2 and sepsis are accompanied by IL-1β overproduction." (PMID 35563475, 2022). "In human studies using plasma specimens from critically ill patients, the expression of inflammasome-related caspase 1, IL-18 and IL-1β mRNA transcripts was significantly higher in patients with sepsis or ARDS, compared with patients with systemic inflammatory response syndrome alone." (PMID 36232959, 2022). "In addition, the deletion of ferritin heavy chain ameliorates the inflammatory burden in the model of sepsis, including reduction of IL-1β, IL-6, IL-12, and IFN-γ and improves survival." (PMID 36357401, 2022). "Moreover, among sepsis patients, those who died had notably elevated cytokines, IL-1β, IL-18, and chemokines, MIP-3α, ENA-78, relative to survivors." (PMID 35291488, 2022). "Furthermore, it was found that LPS stimulation following morphine treatment increased proinflammatory cytokines TNF-α, IL-1β, and IL-6, and reduced serum corticosterone, which act synergistically to enhance the development of sepsis and septic shock." (PMID 35163021, 2022). "IL-1β plays a critical role in the acute phase response and sepsis." (PMID 36059543, 2022). "Furthermore, NLRP3/IL-1β, MuRF1 and MAFbx expression were significantly increased in mice with lipopolysaccharide (LPS)-induced sepsis." (PMID 36405697, 2022). "Besides, 2-DG was proved to improve the survival of sepsis as well as reduce sepsis-related kidney, liver, and cardiac injury by suppressing IL-1β and lactate levels." (PMID 35847986, 2022). "Moreover, with NLRP3 inflammasome and caspase-1 activation, pyroptosis can lead to exteriorization of cellular IL-1β and further enhance the systemic inflammatory response in sepsis." (PMID 35337084, 2022). "In addition, IL-1β activates exosome miR-21 secreted by MSCs to induce macrophage M2 polarization and improve sepsis." (PMID 35082972, 2022). "The cytokine storm, a key feature of sepsis that has been linked to increased risk of mortality, is characterised by a life-threatening systemic inflammation caused by high circulating levels of the proinflammatory cytokines TNF-α, IL-6, and IL-1β." (PMID 35625756, 2022). "Furthermore, the levosimendan pretreatment reduced NO, TNF-α, IL-6, and IL-1β, as well as liver enzymes, in the serum of the sepsis rats, suggesting a hepatoprotective effect." (PMID 36551917, 2022). "IL-1β enhances cell-surface expression of GABAA receptors, increases GABAergic tone, and alters synaptic strength at central GABAergic synapses, thereby contributing to cognitive dysfunction in sepsis-associated-encephalopathy." (PMID 35707033, 2022).
Sepsis (continued). "In line with this, the experimental results from ELISA analysis underlined that sepsis might lead to inflammatory response by elevating the levels of TNF-α, IL-6, IL-1β and IL-18." (PMID 35264055, 2022). "In addition to its antioxidant effects, oxytocin also reduces the production of pro-inflammatory cytokines (such as tumor necrosis factor-alpha, interleukin-1 beta) found in sepsis models." (PMID 35572539, 2022). "Interestingly, anakinra (blocking both IL-1α and IL-1β) has shown promises in treating these patients with hyperinflammatory disorders, sepsis with multiorgan failures." (PMID 35431536, 2022). "Similarly, in vitro studies have reported anti-inflammatory effects of PACAP on microglial cells, which was demonstrated by reduction of iNOS and IL-1β production in an LPS-sepsis model." (PMID 36403002, 2022). "Moreover, the significant up-regulation of miR-21 in MSC-EVs caused by IL-1β can induce the M2 polarization of macrophages by inhibiting the effect of programmed cell death 4 (PDCD4), with similar pattern as miRNA-146a in sepsis." (PMID 35463634, 2022). "Similarly, in sepsis-induced neuroinflammation in mouse hippocampus, LM11A-31 treatment causes a decrease in IL-1β concentrations, associated with a reduction in JNK phosphorylation." (PMID 35309353, 2022). "For example, during the cytokine-induced changes as observed in sepsis, IL-1β (which was part of the cytomix cocktail to stimulate the mouse ECs in our study) is released and adhesion molecules (such as VCAM-1 and SELP) are upregulated from human ECs during inflammation." (PMID 35955534, 2022). "However, the concentration of IL-6 and IL-1β of different genotypes was similar in the T2DM combined with sepsis group and control group." (PMID 35960063, 2022). "Likewise, in vivo TEPP-46 administration inhibited the secretion of IL-1β but increased IL-10 production in LPS-induced sepsis and in a S. typhimurium model of infection." (PMID 34697412, 2022). "Similar to TNF-α, the crucial roles of IL-1β and IL-6 in sepsis are also established." (PMID 35337084, 2022). "lncRNA HOX transcript antisense RNA (HOTAIR) overexpression in sepsis rats could reduce the IL-1β and TNF-α to improve renal function." (PMID 35464083, 2022). "A panel of combined markers further yielded 100% sensitivity and specificity, suggesting that the combination of IL-31, IL-1β, and NLRP3 may provide a promising diagnostic and prognostic panel for sepsis." (PMID 35967871, 2022). "IL-1β is one of the most relevant cytokines for mediating inflammatory injury in sepsis." (PMID 35603184, 2022). "Besides, in an LPS model of sepsis in vivo, we found that LPS-V not only increased IL-1β and TNF-α levels but also shortened survival compared to LPS-B did." (PMID 35523778, 2022). "We detected the expression levels of TNF-α, IL-1β, IL-6, and IL-10 in sera and BALF of septic mice using ELISA, and the results indicated that Fer-1 reduced the upregulation of the expression levels of inflammatory factors caused by sepsis in mice (P < 0.05)." (PMID 35910848, 2022). "Previous studies have shown that obeticholic acid, a derivative of chenodeoxycholic acid, can improve bile acid homeostasis; inhibit the expression of TNF-α, IL-6, and IL-1β; and alleviate sepsis-related liver injury, which suggests that bile acids have a protective effect against sepsis." (PMID 35115021, 2022). "Placental cytokine levels (TNF-α, IL-1β, IL-6) were also increased at 24 h after sepsis induction." (PMID 33632243, 2021). "In consistent with these results, we demonstrated that the recruitment of JMJD3 and NF-κB in the promoter regions of TNF-α, IL-1β, and IL-6 contributed to the upregulation of these pro-inflammatory cytokines via H3K27me3 demethylation, thus promoting inflammatory response in sepsis." (PMID 33413595, 2021). "Furthermore, we observed that among the tested sepsis-associated cytokines (e.g., IFN-γ, IL-1β, TNF-α, and G-CSF), G-CSF and IFN-γ impaired DC development from cultured HSPCs." (PMID 34566996, 2021).